SOX10 (SRY-box transcription factor 10)
Diseases named in the same sentence as SOX10 in open-access papers (continued):
Sharing a sentence is not in itself a finding about the gene and the disease.
melanoma (continued). "We here describe that these features, expression of EGFR, lack of MITF and SOX10, are inherent and occurs independently of drug selection in EGFRHIGH/ERBB3LOW-Invasive melanomas." (PMID 25742786, 2015). "Of note, in human melanoma cell lines in vitro, all antibodies tested but sc-20095 not only recognized SOX9, but also a protein of the molecular weight of SOX10 and detected by a SOX10-specific antibody." (PMID 25629959, 2015). "Thin primary melanomas (such as MM28, Breslow = 0.8 mm) or thick primitive melanomas (such as MM25, Breslow = 16 mm) displayed a proliferative/differentiated ZEB2+ MITF+ SOX10+ phenotype with no or low ZEB1, SOX9 and NGFR expression." (PMID 38519642, 2024). "Additionally, negative staining for NKX2.2, CD99, desmin, S100, SOX10, HMB45, GATA3, CD45 (LCA), CD3, and CD20 further excluded diagnoses of Ewing sarcoma, rhabdomyosarcoma, melanoma, and the majority of non-Hodgkin lymphomas." (PMID 39404971, 2024). "Undifferentiated melanomas are defined as completely lacking conventional histopathological and immunohistochemical melanocytic differentiation (negative for the five commonly used melanoma markers—MelanA, MiTF, HMB45, S100, and SOX10) and displaying a “vimentin-only” phenotype." (PMID 37373134, 2023). "To understand whether MITF promoter–methylated melanoma cells can undergo phenotype switching in NOD/SCID-γ (NSG) mice, we selected 1 cell line that expresses SOX10 (MM383) and 1 that does not express SOX10 (IGR-39)." (PMID 36040798, 2022). "SOX10 directly induces the transcription of IRF4, a negative regulator of IRF1; thus, its inhibition can enhance tumor responsiveness to anti-PD1 therapy, as observed in mice subcutaneously implanted with murine D4M melanoma cells." (PMID 36551603, 2022). "The stable or transient knockdown of CD271 in melanoma cells revealed that the NCSC-like phenotype is maintained by expression of CD271 which in turn controls the levels of downstream targets, e.g., SOX10, FOXD3, and SOX2 (not shown)." (PMID 32878000, 2020). "Moreover, there was no strict correlation between the patterns of SOX9, SOX10, and NEDD9 expression and distribution of pigmented melanomas in all examined stages." (PMID 30642390, 2019). "Thus, SOX10 but not SOX9 is prominently expressed in normal human melanocytes, human giant congenital naevi, and primary melanoma." (PMID 25629959, 2015). "Because expression of SOX-10 and BRAF V600E were negative in all cases, melanoma could be excluded." (PMID 37470853, 2023). "In conventional pan-melanoma-cocktail-negative cases, it is recommended to add, for an appropriate differential diagnosis, other markers such as the microphthalmia transcription factor (MITF) and the SRY-related high-mobility group box transcription factor 10 (SOX10)." (PMID 33801642, 2021). "As melanoma acquire invasiveness, the promoter of SOX9 becomes hypomethylated probably through downregulation of DNA methyltransferase that could partly contribute to its high level of expression in a subset of SOX10 negative metastatic melanoma." (PMID 30642390, 2019). "Since in vivo tumors contain a mix of melanoma and nonmelanoma cells, we also asked whether any correlation with PAX3 or MITF was observed in 53 melanoma cell lines grouped according to four different melanoma phenotypes distinguished by SOX10, SOX9, and MITF expression." (PMID 34819350, 2021).
schwannoma (64 papers, 2008 to 2026). A benign, usually encapsulated slow growing tumor composed of Schwann cells. "For the pathological diagnosis of schwannoma, positive S100 and SOX10 are necessary diagnostic criteria." (PMID 40018446, 2025). "Reduced expression of SOX-10 at the protein and gene levels has been demonstrated in human schwannoma cells, while the loss of SOX-10 expression in Schwann cells leads to them acquiring schwannoma cell characteristics." (PMID 37948527, 2023). "Overall, the results suggest that the loss of SOX10 in Schwann cells leads to cellular abnormalities resembling schwannomas." (PMID 38132479, 2023). "Our prior studies in a fetal glial cell model found that SOX10 indel mutations impair transactivation of glial differentiation and myelination genes, and likely cause schwannoma development through blockade of Schwann cell maturation." (PMID 37821623, 2023). "All variants of schwannoma demonstrate diffuse and strong positivity for S100 and SOX10." (PMID 41281118, 2025). "At least partially, this may be causative for the reduced Sox10 protein levels measured in Hes1/Tle4-transfected S16 Schwannoma cells." (PMID 38791273, 2024). "This resulted in individuals that harbor these SOX10 mutations in Schwann cells and their progenitors in a limited segmental distribution along a single peripheral nerve, which then gave rise to multiple genetically identical schwannomas over time." (PMID 37821623, 2023). "Notably, a previous study reported that loss of SOX10 function contributed to the phenotype of human Merlin-null schwannoma cells, indicating that the mutation of SOX10 might be associated with the initiation of schwannoma." (PMID 33193598, 2020). "And histopathological examination, with typical Antoni A areas and strong S-100 and SOX-10 expression, confirmed a diagnosis of schwannoma." (PMID 40538849, 2025). "Schwannomas and other peripheral nerve sheath tumors usually show S-100/SOX10 positivity, whereas smooth muscle tumors demonstrate desmin and/or α-SMA positivity." (PMID 41431481, 2025). "Both benign schwannomas and neurofibromas typically exhibit diffuse, strong positivity for S100 protein and strong nuclear SOX10 reactivity." (PMID 41306141, 2025). "DCNP stains positive for S100 and SOX10, and similarly, a majority of schwannomas and neurofibromas show a relatively increased expression of both these markers." (PMID 40988822, 2025). "Histopathological analysis confirmed a benign schwannoma exhibiting secondary degenerative changes, supported by positive SOX-10 and S-100 immunostaining and a low Ki-67 proliferation index." (PMID 41030823, 2025). "Immunohistochemistry confirmed a benign schwannoma with secondary degenerative changes, evidenced by SOX-10 and S-100 positivity and a low Ki-67 proliferation index." (PMID 41030823, 2025). "Our findings demonstrate that schwannomas exhibit consistent S100/SOX10 expression and low Ki67 proliferative indices (≤ 15% in cellular areas, otherwise < 1%), aligning with their benign WHO Grade I classification." (PMID 41359213, 2025). "The combined use of S100 and SOX-10 helped to improve the sensitivity and specificity of schwannoma diagnosis." (PMID 40308497, 2025). "Schwannoma/neurofibroma hybrids exhibit strong S100 and SOX10 positivity in schwannomatous areas, whereas the neurofibroma component expresses S100, SOX10, EMA, and GLUT-1." (PMID 40218204, 2025). "Schwannomas exhibit strong, diffuse S100 positivity and SOX10 expression, while neurofibromas show variable S100 expression due to their mixed cellular composition." (PMID 41446319, 2025). "Immunohistochemical (IHC) analysis confirmed these dual components: schwannoma/perineurioma hybrids were positive for S100 and SOX10 in schwannomatous regions, while perineuriomatous areas expressed EMA, Claudin-1, and GLUT-1." (PMID 40218204, 2025).
schwannoma (continued). "These markers help to differentiate SFTs from meningiomas, which typically express epithelial membrane antigen (EMA), and schwannomas, which are positive for S100 and SOX10." (PMID 40559210, 2025). "CD34, C-kit, CAM5.2, desmin, and progesterone receptor were negative, however, cytopathology showed scattered fragments of spindled cells positive for SOX10, consistent with a schwannoma." (PMID 39735038, 2024). "Neurofibroma and schwannoma are distinguished by their consistent expression of S100 and SOX10, while perineurioma lacks S100 expression and instead exhibits membranous staining with EMA, GLUT-1, and Claudin-1." (PMID 39410565, 2024). "Immunohistochemical staining, particularly utilizing tumor markers such as S100 and SOX10, holds decisive significance in accurately diagnosing schwannoma." (PMID 39158355, 2024). "We found strong repression of U1 enhancer activity by Hes1 and of the U3 activity by Tle4 or Hes1 in Sox10-positive S16 Schwannoma cells." (PMID 38791273, 2024). "S100, though highly sensitive (97%) in distinguishing schwannomas, lacks specificity, with SOX10 emerging as the most sensitive and specific biomarker." (PMID 39158355, 2024). "While S100 is significantly expressed in meningiomas and fibromas, SOX10 exhibits expression exclusively in tumors derived from schwannomas and melanocytes." (PMID 39158355, 2024). "Immunofluorescence on 49 schwannomas showed the Schwann cell differentiation marker SOX10 was expressed in both molecular groups but was enriched in neural crest compared to immune-enriched tumors." (PMID 38216587, 2024). "Schwannomas, also known as neurilemmomas or neurinomas of Verocay, are seen as encapsulated benign tumors expressing SC differentiation morphology and markers, including S100 and SOX10 protein, that develop from myelinated peripheral nerves." (PMID 38638689, 2024). "Immunohistochemical markers including CD117, CD56, CD34, S100, SOX10, Calretinin, Desmin, Vimentin, EMA and smooth muscle antigen are associated with Schwannomas and can be used to confirm their diagnosis." (PMID 39558963, 2024). "The expression of Schwann cell differentiation markers S100B and SOX10 was used to identify 7 clusters of schwannoma cells and 6 clusters of microenvironment cells." (PMID 38216587, 2024). "The final pathology showed a solid, submucosal rectal mass that was positive for SOX10 and S100 on immunohistochemistry, supporting our diagnosis of Schwannoma." (PMID 38962623, 2024). "The combined use of Sox10 and S100 helps to improve the sensitivity and specificity of schwannoma diagnosis." (PMID 39213227, 2024). "The majority of schwannomas and neurofibromas showed increased expression of both SOX10 and S100 mRNA." (PMID 38132479, 2023). "Reintroducing the SOX10 gene in schwannoma cells showed a small increase in KROX20 expression, which significantly increased with the introduction of cAMP." (PMID 38132479, 2023). "Immunohistochemical staining of the spindle cells in schwannomas is positive for S-100 protein in cytoplasm, and positive for SOX-10 in nuclear." (PMID 36759886, 2023). "Immunohistochemical staining results of other benign schwannomas showed positivity for S‐100,26, 29, 30 SOX10, Vimentin, and GFAP, and negativity for SMA, EMA, CD34, and CD117." (PMID 36440500, 2023). "Complete negativity for Sox10 was observed in one neurofibroma and in the perineurioma portion of a hybrid perineurioma–schwannoma." (PMID 35622732, 2022). "When overexpressing SOX10 in Merlin-null Schwannoma cells in which the SOX10 level was reduced to restore Merlin tumor suppressor, NFATc4 was activated with nuclear translocation and the cell growth was alleviated." (PMID 35698138, 2022). "The lesional cells tested positive for S-100 and SOX-10 on immunohistochemical analysis, establishing the diagnosis of benign schwannoma." (PMID 36582566, 2022).
schwannoma (continued). "On the other hand, in comparison with both CD13 and EMA, SOX10 expression significantly supported a diagnosis of schwannoma (p < 0.0001) as well as STAT6 staining that of SFT/HPC (p < 0.0001)." (PMID 35212813, 2022). "As for the other types of schwannoma, even epithelioid cell schwannoma is strongly and diffusely stained with S100 protein and SOX10." (PMID 35741273, 2022). "In Schwannoma, NFATc4 and SOX10 synergistically enhanced KROX20 activity and induced P0 transcription to regulate the cell proliferation." (PMID 35698138, 2022). "All of the retrieved schwannomas stained positive for SOX10 (15/15), as well as all the SFT/HPCs for STAT6 (20/20)." (PMID 35212813, 2022). "SOX10: SOX10 immunoreactivity was restricted to the nucleus of GCTs and Schwannomas and was of high intensity for all cells." (PMID 35323240, 2022). "Whereas schwannomas and epithelioid MNSTs that were diffusely Sox10-positive and apparently derived from Schwann cells were completely negative for claudin-1, perineuriomas and perineurial MNSTs showed moderate to strong claudin-1 positivity." (PMID 35622732, 2022). "Whilst SOX10 has also been examined in human Schwann cells, this has been largely limited to the study of pathologies such as Schwannoma." (PMID 32303273, 2020). "After subtotal resection it was diagnosed as a SOX-10/S100 positive schwannoma with ancient change and rare mitotic activity along with a high Ki-67 of 10%." (PMID 31806041, 2019). "On IHC, hybrid schwannomas/perineuriomas demonstrate S100 protein and SOX10 in the schwannomatous areas, and embryonic membrane antigen (EMA), Claudin-1 and Glucose Transporter 1 (GLUT-1) in the perineuriomatous areas." (PMID 28526004, 2017). "Some studies point to an association between SOX10 and S100B; for instance, knockdown of SOX10 in Schwannoma cells drastically reduces S100B levels." (PMID 25536222, 2014). "We have previously reported a case of apparent transdifferentiation of RT4D6 Schwannoma cells into smooth muscle cells upon introduction of an siRNA specific to the transcription factor Sox10." (PMID 18786246, 2008). "We took advantage of RNAi technique to screen for genes in a Schwannoma cell line that are down-regulated upon introducing small interfering RNA (siRNA) specific for Sox10." (PMID 18786246, 2008). "By combining RNA interference technique and DNA microarray technology, we have identified a set of genes that show significant down-regulation upon introduction of Sox10 specific siRNA into Schwannoma cells." (PMID 18786246, 2008). "Histopathology confirmed schwannoma with S-100 and SOX10 positivity and a low Ki-67 index (~3%)." (PMID 42094961, 2026). "However, others reported up to 49% of MPNSTs as being SOX10-positive, as well as diffuse expression in neurofibromas and Schwannomas." (PMID 40507250, 2025). "On immunohistochemistry, S100 and SOX10 were diffusely positive, consistent with schwannoma." (PMID 40255781, 2025). "MMP9 initially concentrated around SOX-10 + schwannoma cells." (PMID 38887507, 2024). "Further immunohistochemical analysis was positive for S100 and SOX10 consistent with a Schwannoma." (PMID 39558963, 2024). "To elucidate if Sox10 expression is indeed regulated by Tle4 and Hes1, we used S16 Schwannoma cells and quantified the signal intensity of endogenous Sox10 immunofluorescence in these cells by flow cytometry after transfecting them with control plasmids or plasmids encoding Hes1, Tle4, or both." (PMID 38791273, 2024). "Immunostaining of AS is positive for S-100 and SOX10, as for other schwannomas." (PMID 38578531, 2024). "Histopathologic evaluation of the multiple resected tumors in both patients revealed schwannomas with classic histological features including both compact Antoni A and loose microcystic Antoni B areas, along with diffuse positivity for S100 and SOX10 immunostaining." (PMID 37821623, 2023).
schwannoma (continued). "Furthermore, these tumors clustered together with SOX10-mutant sporadic schwannomas which we previously found are epigenetically distinct from NF2-mutant schwannomas." (PMID 37821623, 2023). "SOX-10 is an additional marker of schwannoma that is expressed in the majority of cases." (PMID 35741273, 2022). "Hybrid schwannomas/neurofibromas demonstrate the S100 protein and SOX10 in the schwannomatous areas while the neurofibroma component, being composed of a polymorphic cell population, demonstrates positivity for S100, SOX10, EMA and GLUT1." (PMID 28526004, 2017). "SOX10 is a transcription factor in neural crest formation and specification to schwannian and melanocytic lineages, which is starting to replace S100 as a more sensitive and specific marker for schwannoma and neurofibroma in the present authors’ practices." (PMID 24131748, 2013). "Positive staining for S100, SOX10, and CD34, coupled with low Ki67 proliferation index, aligns with typical Schwannoma profiles." (PMID 39507764, 2024). "Immunoreactivity to CD68, HLA-DR, CD163, CD40 and CD11c (APC phenotype) and markers of neural crest cell (NCC) origin S100, SOX10, NSE and GAP43 in 23 cases of GCTs and 10 cases of Schwannomas were evaluated." (PMID 35323240, 2022). "Immunohistochemical analysis for CD13, epithelial membrane antigen, SOX10, and STAT6 was carried out in a large cohort of primary meningeal tumors comprising 225 meningiomas, 15 schwannomas, and 20 solitary fibrous tumor/hemangiopericytomas." (PMID 35212813, 2022). "Both neurofibroma and schwannoma are positive for SOX10 and S100 protein, negative for STAT6; meanwhile, neurofibroma is also positive for CD34." (PMID 41226013, 2025). "In contrast, markers such as S100, SOX10, EMA, CD99, OLIG2, and GFAP were negative, thereby excluding alternative diagnostic possibilities such as schwannoma, meningioma, and glial neoplasms." (PMID 40559210, 2025). "Pathological results confirmed the tumor to be a classic schwannoma, with positive expression of S-100 and SOX-10 proteins and negative expression of epithelial membrane antigen." (PMID 40538849, 2025). "Unlike schwannomas, neurofibromas demonstrate CD34 protein positive rather than SOX-10 strong peripheral staining seen in schwannomas." (PMID 40538849, 2025). "GISTs are consistently positive for CD117, DOG1, and CD34, whereas schwannomas, as in our case, express S100 and SOX10 while being negative for CD117 and DOG1." (PMID 40507589, 2025). "Schwannomas consistently express S100 and SOX10, while being negative for CD117, DOG1, and CD34, distinguishing them from GIST." (PMID 40507589, 2025). "The diagnosis is confirmed through immunohistochemical studies, where schwannomas typically stain positive for S-100 and SOX-10, unlike CD34, CD117, and desmin, which are markers for leiomyomas." (PMID 39554676, 2024). "The classic schwannoma was the only one that was completely negative for claudin-1 and showed strong reactivity for Sox10 and moderate reactivity for GFAP." (PMID 35622732, 2022). "In hybrid perineurioma/schwannoma, Sox10 and GFAP expression was restricted to the part of the schwannoma, whereas the perineurioma regions expressed claudin-1 moderately to strongly and were negative for Sox10 and GFAP." (PMID 35622732, 2022). "Additionally, immunohistochemistry revealed strong positivity for S100 and SOX10, which is typical of schwannomas, and negative staining for markers like c-KIT, DOG1, and CD34, which are associated with GISTs." (PMID 40507589, 2025). "Also, even if schwannomas typically express S100 and SOX10, immunohistochemical evaluation was not performed on the initial biopsy due to the limited material obtained via EUS-FNA." (PMID 40507589, 2025). "This lack of SMA expression in incisional biopsy samples could direct the diagnosis to tumors of neural origin, such as MPNST or schwannoma, which both express S100 and SOX10 and are typically negative for myogenic markers." (PMID 36292216, 2022).
schwannoma (continued). "Immunohistochemistry was positive for SOX10 and negative for CD34, DOG1, and desmin, confirming schwannoma." (PMID 41230329, 2025). "Based on our results, we consider Sox10, claudin-1, GFAP, and Ki-67 useful in the diagnosis of NST, whereas CNPase was negative in almost all cases, except for classical schwannoma, which was only mildly positive." (PMID 35622732, 2022). "However, GFAP, SOX10, CD24, EMA, CKAE1/3, and PR negativity rule out meningiomas, glial tumors, schwannomas, metastatic melanomas or carcinomas." (PMID 41302074, 2025).